PIK3R1 (phosphoinositide-3-kinase regulatory subunit 1)
Description:
Binds to activated (phosphorylated) protein-Tyr kinases, through its SH2 domain, and acts as an adapter, mediating the association of the p110 catalytic unit to the plasma membrane. Necessary for the insulin-stimulated increase in glucose uptake and glycogen synthesis in insulin-sensitive tissues. Plays an important role in signaling in response to FGFR1, FGFR2, FGFR3, FGFR4, KITLG/SCF, KIT, PDGFRA and PDGFRB. Likewise, plays a role in ITGB2 signaling. Modulates the cellular response to ER stress by promoting nuclear translocation of XBP1 isoform 2 in a ER stress- and/or insulin-dependent manner during metabolic overloading in the liver and hence plays a role in glucose tolerance improvement.
Synonyms: GRB1; p85-ALPHA; p85; p85alpha; AGM7; IMD36
Tractability: Small molecule: a drug acting on it is in phase 2 or 3 trials; a structure with a bound ligand is known; a high-quality ligand is known; it has a binding pocket of medium quality; it belongs to a druggable protein family. Antibody: its Gene Ontology location is reachable by antibodies, with high confidence. PROTAC: UniProt records ubiquitination sites on it; ubiquitination databases record sites on it; its protein half-life has been measured; a small molecule that binds it is known.
Target class: Enzyme
Safety:
Unwanted effects reported when the protein is acted on. In parentheses: how it was acted on, where the effect was seen, and who reports it.
hyperglycemia (source: ClinPGx)
leukopenia (source: ClinPGx)
Gene: Protein-coding gene on chromosome 5 (68,215,740 to 68,301,821, forward strand). Ensembl gene ENSG00000145675.
Subcellular location: Cytoplasm
Subcellular location (Human Protein Atlas): Cytosol
Pathways (Reactome):
Signal Transduction: Activated NTRK2 signals through PI3K; Activated NTRK3 signals through PI3K; CDC42 GTPase cycle; Downstream signal transduction; Erythropoietin activates Phosphoinositide-3-kinase (PI3K); Extra-nuclear estrogen signaling; G alpha (q) signalling events; GAB1 signalosome; IRS-mediated signalling; MET activates PI3K/AKT signaling; PI-3K cascade:FGFR1; PI-3K cascade:FGFR2; PI-3K cascade:FGFR3; PI-3K cascade:FGFR4; PI3K Cascade; PI3K events in ERBB2 signaling; PI3K events in ERBB4 signaling; PI3K/AKT activation; PI5P, PP2A and IER3 Regulate PI3K/AKT Signaling; PIP3 activates AKT signaling; RAC1 GTPase cycle; RAC2 GTPase cycle; RAC3 GTPase cycle; RAF/MAP kinase cascade; RHOA GTPase cycle; RHOB GTPase cycle; RHOC GTPase cycle; RHOD GTPase cycle; RHOF GTPase cycle; RHOG GTPase cycle; RHOJ GTPase cycle; RHOU GTPase cycle; RHOV GTPase cycle; RND1 GTPase cycle; RND2 GTPase cycle; RND3 GTPase cycle; Signaling by ALK; Signaling by LTK; Signaling by SCF-KIT; VEGFA-VEGFR2 Pathway
and 38 more pathways
Gene Ontology:
Molecular function: ErbB-3 class receptor binding; insulin binding; insulin receptor binding; insulin-like growth factor receptor binding; neurotrophin TRKA receptor binding; phosphatidylinositol 3-kinase regulator activity; phosphotyrosine residue binding; protein binding; protein phosphatase binding; 1-phosphatidylinositol-3-kinase regulator activity; enzyme-substrate adaptor activity; phosphatidylinositol 3-kinase activator activity; phosphatidylinositol 3-kinase binding; phosphatidylinositol kinase activity; transmembrane receptor protein tyrosine kinase adaptor activity; insulin receptor substrate binding; kinase activator activity; kinase regulator activity; phosphatidylinositol 3-kinase regulatory subunit binding; protein heterodimerization activity
Biological process: cellular response to insulin stimulus; cytokine-mediated signaling pathway; growth hormone receptor signaling pathway; insulin-like growth factor receptor signaling pathway; interleukin-18-mediated signaling pathway; natural killer cell mediated cytotoxicity; negative regulation of apoptotic process; phosphatidylinositol 3-kinase/protein kinase B signal transduction; positive regulation of endoplasmic reticulum unfolded protein response; positive regulation of protein import into nucleus; positive regulation of RNA splicing; positive regulation of smooth muscle cell proliferation; positive regulation of transcription by RNA polymerase II; protein polyubiquitination; protein stabilization; regulation of toll-like receptor 4 signaling pathway; response to endoplasmic reticulum stress; T follicular helper cell differentiation; B cell differentiation; immune response; insulin receptor signaling pathway; intracellular glucose homeostasis; negative regulation of stress fiber assembly; phosphatidylinositol phosphate biosynthetic process; positive regulation of D-glucose import; and 7 more
Cellular component: cytoplasm; membrane; phosphatidylinositol 3-kinase complex, class IA; cytosol; nucleus; perinuclear region of cytoplasm; phosphatidylinositol 3-kinase complex; plasma membrane; cell-cell junction; cis-Golgi network; perinuclear endoplasmic reticulum membrane
Genetic constraint (gnomAD): Loss-of-function variants: 17 observed, 70.34 expected, observed/expected ratio (o/e) 0.24, 90% interval 0.16 to 0.36. The upper end of that interval is the gene's LOEUF score, 0.36, which puts it in group 1 of 6, group 1 being the genes least tolerant of losing a copy. Missense variants: 480 observed, 735.87 expected, observed/expected ratio (o/e) 0.65, 90% interval 0.6 to 0.7. Synonymous variants: 244 observed, 273.75 expected, observed/expected ratio (o/e) 0.89, 90% interval 0.8 to 0.99.
Gene-disease validity (ClinGen):
ClinGen rates the evidence that PIK3R1 causes each of these diseases.
PIK3R1-related immunodeficiency and SHORT syndrome (autosomal dominant): Definitive. A group of disorders caused by a variation in PIK3R1 gene that produces a structurally altered but present p85α protein, disrupting PI3K signaling and leading to features such as immune deficiency, autoimmunity, short stature, and distinct facial and skeletal features.
agammaglobulinemia 7, autosomal recessive (autosomal recessive): Limited.
Cancer hallmarks: invasion and metastasis (suppresses); suppression of growth (promotes); cell replicative immortality (suppresses)
Homologues: Orthologues: chimpanzee PIK3R1 (99% identical), macaque PIK3R1 (99% identical), guinea pig PIK3R1 (97% identical), mouse Pik3r1 (96% identical), dog PIK3R1 (96% identical), rabbit PIK3R1 (94% identical), tropical clawed frog pik3r1 (82% identical), zebrafish pik3r1 (79% identical), pig PIK3R1 (60% identical), rat Pik3r1 (59% identical). Paralogues in human: PIK3R2 (59% identical), PIK3R3 (48% identical).
Diseases named in the same sentence as PIK3R1 in open-access papers:
PIK3R1 is named in the same sentence as 288 diseases in open-access papers, as found by Europe PMC text mining. Sharing a sentence is not in itself a finding about the gene and the disease. The quoted sentences say what the papers report.
breast carcinoma (96 papers, 2007 to 2025). "Investigations performed on other cancer types demonstrated PIK3R1 copy number loss in 23% of breast cancers, as well as in 24% and 36% of primary and metastatic prostate cancers, respectively." (PMID 39858051, 2025). "Lower levels of PIK3R1 expression are linked to poorer survival outcomes in breast cancer patients and contribute to tumorigenic transformations in breast cancer models." (PMID 40657399, 2025). "Low PIK3R1 expression has previously been linked to advanced histological grade and/or clinical stage in other carcinomas, like in breast cancer, neuroblastoma, hepatocellular cancer, and others." (PMID 39858051, 2025). "Identification of breast cancer patients with PIK3R1 mutations presents an opportunity to select individuals poised to derive greater benefit from PI3K pathway inhibitors, aligning with the principles of precision medicine." (PMID 38172946, 2024). "Genetic alterations in PIK3R1, encompassing both somatic mutations and copy number variations, have been discerned in breast cancer." (PMID 38172946, 2024). "As a predictive biomarker, PIK3R1 mutations have been linked to diverse clinical outcomes in breast cancer patients." (PMID 38172946, 2024). "Amplification of the PIK3CA gene locus and other rare genetic alterations, such as PIK3CB amplification or PIK3R1 inactivating mutations, have been identified, further highlighting the complexity of this pathway’s involvement in breast cancer." (PMID 39850811, 2024). "Of significance is the association of PIK3R1 mutations with specific breast cancer subtypes, suggesting potential implications for disease stratification." (PMID 38172946, 2024). "The mutation of PIK3R1 gene in breast cancer, endometrial cancer, and urothelial carcinoma can lead to pathogenesis." (PMID 36688087, 2023). "Mutations in PTEN and PIK3R1 have been described in different histological types of canine mammary tumors (both benign and malignant), while AKT1 mutations were exclusively observed in complex carcinomas, suggesting that they are tissue-specific." (PMID 37835752, 2023). "It has been suggested that somatic mutations of PIK3R1 (17%), one of the key genes of lipid metabolism, are prevalent and diverse in breast cancer patients." (PMID 34408553, 2021). "It is important to note that in this study on Chinese breast cancer patients the frequency of PIK3R1, AKT1, AKT2, AKT3, and PDK1 mutations was higher than that observed in the TCGA data set." (PMID 32210163, 2020). "Reduced PIK3R1 expression associates with poorer survival of breast cancer patients and tumorigenic transformation in breast cancer models." (PMID 30755611, 2019). "Together, we successfully created an onco-genotype spectrum of PIK3CA and PIK3R1 impactful mutations, and explored their clinical associations in breast cancer." (PMID 29636477, 2018). "This association was first tested in the HBCx-22 TamR PDX, established from a ER+ breast cancer with a PIK3R1 mutation and PTEN protein loss, and rendered resistant to tamoxifen in vivo." (PMID 30038706, 2018). "To summarize, PI3K pathway activation can be induced by impactful PIK3CA or PIK3R1 mutations in breast cancer." (PMID 29636477, 2018). "PIK3R1 under-expression has previously been shown to be an independent prognostic marker in breast cancer and low PIK3R1 expression has been linked to high grade lung cancer." (PMID 26501081, 2015). "Point mutations in and deletions of the PIK3R1 gene have been reported in up to 20% of endometrial cancer cases and in 2.2% of breast cancers." (PMID 26501081, 2015). "These new results suggest that PIK3CA mutations and PIK3R1 underexpression are associated with opposite prognostic impacts on breast cancer patient survival." (PMID 24229379, 2013). "Mostly point mutations and deletions have been reported for PIK3R1, but much less frequently in breast cancer (<5% of cases) than in other cancer types, such as endometrial cancer (about 20% of cases)." (PMID 24229379, 2013).
breast carcinoma (continued). "PIK3R1 has also been recently found to be mutated in breast cancer, but with a considerably lower frequency (about 3%) than PIK3CA." (PMID 24229379, 2013). "We showed that miR-190a-3p, a key regulator of gene expression and pathways important in breast cancer, is potentially involved in the regulation of COL4A1, MAPK3, PIK3CG, and PIK3R1, all of which are integral to pathways associated with breast cancer progression." (PMID 39850811, 2024). "However, the involvement of PIK3R1 in the PI3K/AKT pathway in breast cancer should be further investigated because PIK3R1 is a gene encoding a subunit of the PI3K protein." (PMID 35482141, 2022). "PIK3CA, PIK3CB and PIK3R1 mutations are frequently detected in breast cancer." (PMID 36010585, 2022). "Loss of PIK3R1 is an effective therapeutic mechanism for PIK3CA‐positive breast cancers." (PMID 32419250, 2020). "Moreover, the lower level of PIK3R1 is associated with a poor survival rate in patients with breast cancer." (PMID 31938022, 2020). "Indeed a recent survey of the landscape of somatic mutations in Chinese breast cancer patients suggests evidence supporting the driver candidacy of PIK3R1 in oncogenesis." (PMID 33319839, 2020). "PIK3R1 has a lower frequency mutation than PIK3CA in breast cancer." (PMID 31777591, 2019). "Mutations in PIK3R1 have been found in breast cancer and may result in the generation of a neoantigen." (PMID 31100936, 2019). "Recently, it has been found that PIK3R1 is mutated in 3% of breast cancer cell lines." (PMID 30372442, 2018). "PIK3CA mutations and PIK3R1 underexpression show opposite effects on patient outcome and could become useful prognostic and predictive factors in breast cancer." (PMID 24229379, 2013). "However, the fact that PIK3R1 mutations are rare in breast cancer indicates that PIK3R1 mRNA/p85α expression loss is the main deregulation occurring in breast tumors, particularly in HR- breast tumors." (PMID 24229379, 2013). "For instance, PIK3R1 has been identified as a direct target of miR-155 in breast cancer and B lymphocytes, where it promotes tumor growth by activating glucose metabolism 78-80." (PMID 40657399, 2025). "Low PIK3R1 mRNA expression is associated with unfavorable prognoses in breast cancer patients, increased PI3K signaling, and the tumorigenic transformation of breast cancer models." (PMID 39858051, 2025). "In breast cancer, the downregulation and hypermethylation of PIK3R1 correlate with poor patient outcomes, suggesting its utility as a diagnostic and prognostic biomarker for breast cancer." (PMID 40657399, 2025). "The PI3K signaling pathway, in which PIK3R1 is a critical component, stands out as a crucial therapeutic target in breast cancer." (PMID 38172946, 2024). "In the realm of breast cancer, PIK3R1 has emerged as a prospective predictive biomarker, offering valuable insights into disease prognosis and treatment responsiveness." (PMID 38172946, 2024). "The enhancement of immune function through the targeting of PIK3R1 is a significant mechanism by which this combination exerts its anti‐breast cancer effects." (PMID 38863309, 2024). "Through a comprehensive analysis encompassing multiple genomic changes within the PI3K pathway, including not only PIK3R1 mutations but also mutations in PIK3CA and PTEN, a more nuanced understanding of the molecular landscape of breast cancer emerges." (PMID 38172946, 2024). "The relation between somatic mutations and prognosis was determined and mutations in PIK3R1 and DDR1 were found to be associated with poor outcomes in HR+ breast cancer." (PMID 38977697, 2024). "In ovarian cancer and colon cancer, PIK3R1 gene played a role of an oncogene, while in hepatocellular carcinoma and breast cancer, it played as a tumor suppressor gene." (PMID 36688087, 2023). "Based on these results and cross referencing with the literature, we determined PIK3R1, a reported target in breast cancer, acts as a direct target of miR-155 in FLT3-ITD+AML." (PMID 36605494, 2023).
breast carcinoma (continued). "Mutations in PIK3R1, which encodes the p85α regulatory subunit of the PI3K, have also been identified in HR+ breast cancer." (PMID 35482141, 2022). "In a study on 458 samples of breast cancer, 151 samples had PIK3CA mutations (33.0%), 10 samples had PIK3R1 mutations (2.2%), and 283 samples had PIK3R1 underexpression (61.8%)." (PMID 35482141, 2022). "PIK3R1 down-regulation was found in human breast cancer and, deletion of liver-specific Pik3r1 led to progression of PI3K pathway-activated hepatocellular carcinoma." (PMID 35164019, 2022). "In breast cancer, exosomal miR-221-3p secreted by cancer cells can downregulate phosphoinositide-3-kinase regulatory subunit 1 (PIK3R1) and inhibit the PI3K/Akt signaling pathway to promote adriamycin resistance." (PMID 35592419, 2022). "PIK3R1 is suggested to be the potential gene for OA in overcoming tamoxifen resistance in breast cancer therapy." (PMID 35482141, 2022). "A recent study demonstrated that miR-221-3p confers drug resistance of breast cancer cells to adriamycin by targeting PIK3R1 in vitro and in vivo." (PMID 35090460, 2022). "Among genes known to be related to human breast cancer, we previously reported the reduced expression of Pten (on 1q52, 0.53-fold), Pik3r1 (on 2q12, 0.61-fold), and Map3k1 (on 2q14, 0.75-fold) in mammary carcinomas of (SD×COP)F1 rats." (PMID 34388197, 2021). "The next pathway, ESR1, which was mutated in breast cancer, received microenvironment factor S100A4 to regulate TF ETS1 and SMAD3 through signaling transduction proteins ZNF516, PIK3R1, IDH1, and AKT1." (PMID 33802957, 2021). "Almost two-thirds of breast cancer show decreased expression of PIK3R1, which encodes for p85α, while increased expression of PIK3R2, which encodes for p85β, is seen in 45% of breast cancers." (PMID 34769309, 2021). "Reportedly, PIK3R1 promotes the migration and invasion of breast cancer cells through modulating PI3K/AKT signaling." (PMID 34765599, 2021). "Hs578T breast cancer cells carry a mutation in the PI3K regulatory subunit p85α, PIK3R1, that leads to hyper-activation of the PI3K pathway." (PMID 32111826, 2020). "PIK3R1 is in a DriveWays module containing PIK3CA and ERBB2, both of which are associated with breast cancer through the CMbreast reference set." (PMID 33319839, 2020). "A recent study explored the oncogenic activity induced by loss of the tumor suppressor PI3K-p85α (PIK3R1): knockdown of this gene transforms human mammary epithelial cells, and its genetic ablation accelerates a mouse model of HER2/neu-driven breast cancer." (PMID 32210163, 2020). "PIK3R1 shRNA-mediated knockdown in human breast cancer cell lines can also augment AKT signaling and anchorage-independent growth, illustrating a tumor suppressive role for p85α in breast cancer." (PMID 32630372, 2020). "In this study, we show for the first time that CapG contributes to chemotherapy resistance especially paclitaxel resistance in breast cancer by epigenetically enhancing PIK3R1/P50 transcription, resulting in increased activation of PI3K pathway." (PMID 31660072, 2019). "In accordance, we found the expression level of CapG correlated with PIK3R1/p50α levels in a panel of breast cancer cells." (PMID 31660072, 2019). "Here, we determine that somatic mutations in PIK3CA (44%), PIK3R1 (17%), AKT3 (15%), and PTEN (12%) are prevalent and diverse in Chinese breast cancer patients, with 60 novel mutations identified." (PMID 29636477, 2018).